IL6 (interleukin 6)
Diseases named in the same sentence as IL6 in open-access papers (continued):
Sharing a sentence is not in itself a finding about the gene and the disease.
ischemic stroke (continued). "Our results showed higher MDA, IL-6, and TNF-α levels, and lower SOD, SIRT1, and BMAL1 levels in ischaemic stroke patients compared to control patients (P < 0.05)." (PMID 38245621, 2024). "In animal models of ischemic stroke, cytokines were upregulated, which triggered proinflammatory (e.g., interleukin [IL]-1β, tumor necrosis factor [TNF], and IL-6) and anti-inflammatory (transforming growth factor-β and IL-10) mechanisms." (PMID 38206990, 2024). "Among the four subgroups, the content of MDA, IL-6, and TNF-α was highest in patients with ischaemic stroke onset from subgroup 2 (06:00–11:59), while the expression levels of SOD, BMAL1, and SIRT1 were lowest in patients with ischaemic stroke in subgroup 2." (PMID 38245621, 2024). "Specifically, patients with ischemic stroke onset from subgroup 2 (6:00–11:59) exhibited significantly increased levels of MDA, IL-6, and TNF-α, and decreased activity of SOD." (PMID 38245621, 2024). "The NIHSS score, infarct volume and the levels of NLRP1, IL-6, TNF-α, and IL-1β of ischemic stroke patients in the mRS score ≥ 3 group were remarkably elevated than the ischemic stroke patients in the mRS score ≤ 2 group." (PMID 37000063, 2023). "To further investigate the relationship between NLRP1 and inflammatory factors in ischemic stroke patients, we measured the serum levels of NLRP1, CRP, IL-6, TNF-α, and IL-1β by ELISA." (PMID 37000063, 2023). "The NIHSS score, the mRS score after 90 days and the levels of NLRP1, CRP, TNF-α IL-6 and IL-1β of ischemic stroke patients in the ASITN/SIR grade 0 to 2 group were remarkably elevated than the ischemic stroke patients in ASITN/SIR grade 3 to 4 group." (PMID 37000063, 2023). "The NIHSS score, infarct volume, and the levels of IL-6, TG, and HDLC of ischemic stroke patients in the mRS score ≥ 3 group were remarkably elevated than the ischemic stroke patients in the mRS score ≤ 2 group (P < 0.05)." (PMID 36875689, 2023). "A total of 218 patients with ischemic stroke and 198 healthy controls were enrolled and an in-house ELISA was developed with linear peptides derived from VEGFR1, LOX-1, IL6, and IL8 to detect their IgG levels in plasma." (PMID 36741286, 2023). "In previous studies, proinflammatory cytokines such as IL-6 and TNF-α that glial cells secrete, induce inflammation in ischemic stroke." (PMID 37107160, 2023). "The NIHSS score, infarct volume and the levels of NLRP1, IL-6, TNF-α, and IL-1β of ischemic stroke patients in the mRS score ≥ 3 group were remarkably elevated than the ischemic stroke patients in the mRS score ≤ 2 group (P < .05)." (PMID 37000063, 2023). "IL-6, AKT1, VEGFA, STAT3, TNFα, etc., were the core target of phenolic acids in preventing ischemic stroke." (PMID 36778026, 2023). "E plus P attenuated the expression of ischemic stroke-induced proinflammatory chemokines chemokine ligand 2 (CCL2), chemokine ligand 5 (CCL5), and interleukin 6 (IL-6)." (PMID 36569944, 2022). "In the occurrence of ischemic stroke, monocyte macrophages and T lymphocytes are stimulated to produce inflammatory cytokines, such as tumor necrosis factor α (TNF-α), interleukin 6 (IL-6), and interleukin 1 (IL-1), which have immunomodulatory function." (PMID 35340417, 2022). "Previous reports showed that JQ1-treated animals exhibit a marked reduction in the expression of pro-inflammatory mediators IL-1β, IL-6, IL-17, IL-18, and TNF-α in the brain in rodent ischemic stroke models." (PMID 35761277, 2022). "Microglia release proinflammatory cytokines such as IL-1β, IL-6, and TNF-α in the acute phase of ischemic stroke, impeding postinjury neural regeneration and producing poorer long-term neurological outcomes." (PMID 36338577, 2022).
ischemic stroke (continued). "Additionally, IL-6 also been reported to facilitate post-traumatic healing in the CNS through repair of endothelial cells, which also demonstrates that IL-6 may enhance revascularization or angiogenesis after ischemic stroke." (PMID 35173738, 2022). "Published studies have paid little attention to the correlations between Lp-PLA2 activity (or mass) and other ischemic stroke biomarkers, including CRP, MMPs, IL-6, TNF-α, VCAM1, ICAM1, S100B, vWF, BNGF, and MCP1." (PMID 36313479, 2022). "The expression of pro-inflammatory cytokines (IL-1β, IL-6, IL-8, TNF-α) in the cortex of ischemic stroke mice was detected after the occurrence of cerebral ischemia." (PMID 35173738, 2022). "In ischemic stroke, manifestation of downregulated NF-κB was supplemented by the knockdown of TNF-α, IL-6 and IL-1β." (PMID 33658008, 2021). "Here, we sought to examine the concentrations of inflammatory cytokines (IL-1β, IL-6, and IL-10) and growth factors (VEGF, BDNF/TrkB and TGF-β) 24-h and 30 days after ischemic stroke." (PMID 34408211, 2021). "In conclusion, we have identified that the acute upregulation of endostatin, IL-6, and TNF-R1 after ischemic stroke can predict long-term mortality." (PMID 33578805, 2021). "We observed upregulation of IL-6, strong activation of microglia and accompanying BBB disruption during ischaemic stroke." (PMID 33953171, 2021). "Earlier studies have shown that after ischemic stroke, Zileuton suppresses NF-κB activation and the levels of inflammatory cytokines were decreased (LTB4, TNF-α, IL-6, IL-1β)." (PMID 33878031, 2021). "The strengths of this study are the short median time interval between ischemic stroke debut and blood sampling (<8 h), the sampling of blood prior to thrombolysis, the discrimination of ischemic stroke from TIA patients, and the inclusion of IL-6 and S100B." (PMID 32595585, 2020). "In an ischemic stroke mouse model, ORM inhibited the production of the inflammatory cytokines IL-1β, IL-6, and TNF-α." (PMID 33013889, 2020). "It has been shown that after an ischemic stroke, the blood-brain barrier integrity was influenced by microglia via an up-regulation of pro-inflammatory cytokines including IL-1b, TNF-a, and IL-6." (PMID 32501292, 2020). "Other anti-inflammatory therapies have been investigated in AMI and ischemic stroke, such as colchicine, anti-CD18 agents and agents targeting IL-1 or IL-6." (PMID 32932587, 2020). "Gm4419 promoted neuroinflammation by inducing IκB phosphorylation and NF-κB signaling activation after ischemic stroke, and the levels of tumor necrosis factor-α (TNF-α), interleukin-1β (IL-1β) and IL-6 were increased." (PMID 33613191, 2020). "Other researches prove that proinflammatory cytokines such as IL-1b, IL-6, and TNF-a are released by microglia and upregulate after ischemic stroke." (PMID 32382569, 2020). "Hs-CRP is a systemic inflammatory marker that is produced in large amount by hepatocytes in response to interleukin-1 (IL-1), interleukin-6 (IL-6) and tumor necrotic factor-α (TNF-α) after ischemic stroke." (PMID 31814936, 2019). "TAOK1 expression was significantly down-regulated, however, IL-1β, IL-6 and IL-8 expression were up-regulated in MCAO rat model and OGD-induced neural stem cell model of ischemic stroke." (PMID 31652447, 2019). "In line with the previous studies, ischemic stroke induced massive production of TNF-α, IL-1β, and IL-6." (PMID 29544517, 2018). "As innate immunocytes, microglia were excessively activated and released robust inflammatory cytokines, such as IL-1, IL-6, TNF, and iNOS, immediately after ischemic stroke, which contributed to neuronal apoptosis and thus aggravated brain injury." (PMID 30001721, 2018). "Ischemic stroke significantly increased protein levels of TNF-α in BALF and plasma, as well as of IL-6 in plasma." (PMID 30290827, 2018).
ischemic stroke (continued). "Additionally, a recent study showed that Klotho gene overexpression significantly decreased IL-6 production in HUVECs with or without inflammatory challenge, and IL-6 receptor polymorphisms contributed to neurological status in ischemic stroke patients." (PMID 29403373, 2017). "Serum levels of CRP, IL-6, IL-10, and IL-23 were significantly correlated with lesion volume and/or NIHSS in patients with ischemic stroke." (PMID 27682880, 2017). "Secondly, FGF10 treatment in vivo decreased neuronal apoptosis and inhibited NF-κB signaling activation during ischemic stroke and thereby neuroinflammation (TNF-α and IL-6 production)." (PMID 26813160, 2016). "Interleukin-6 (IL-6) interleukin-1 beta (IL-1b), and tumor necrosis factor-alpha (TNF-α) are one of the important atherogenic markers in ischemic stroke patients." (PMID 26075263, 2015). "In conclusion, the results suggest that CXCL10 and IL-6 have important roles in the occurrence and progression of MCAO-induced ischemic stroke." (PMID 25333814, 2015). "The present study found elevated IL-1β, IL-6 and TNF-α level in CSF at the sixth hour from ischemic stroke onset." (PMID 21450100, 2011). "In addition to major cytokines like IL-1β, IL-6, TNF-α, and IL-10, several other inflammatory mediators play significant roles in ischemic stroke." (PMID 40869247, 2025). "To investigate whether GJC-CDs are involved in the inflammatory response in ischemic stroke, we examined the levels of TNF-α, IL-1β, IL-6, and IL-10 in the serum of each group of mice." (PMID 40573265, 2025). "The absence of ADAMTS13 in mice with ischemic stroke has been correlated with increased myeloperoxidase activity and expression of pro-inflammatory cytokines such as interleukin-6 and tumor necrosis factor-α." (PMID 40217918, 2025). "IL-6 contributes to vascular inflammation by promoting the expression of adhesion molecules and MMPs, leading to BBB breakdown and further neuronal damage in ischemic stroke." (PMID 40949500, 2025). "Previous studies have demonstrated that newly repopulated microglia had reduced expression of inflammatory markers (e.g., IL-1β, IL-6, TNF-α and CD86), and upregulation of neuroprotective factors (e.g., CD206, TGF-β, and IL-10) in response to ICH ischemic stroke in ageing." (PMID 40777042, 2025). "Our study aims to synthesize current knowledge on the roles of IL-6 and TNF-alpha in ischemic stroke, explore their potential as biomarkers for disease progression and prognosis, and correlate the degree of disability in ischemic stroke patients with plasma concentrations of these two biomarkers." (PMID 39859987, 2025). "Considering the pivotal role of microglia in neuroinflammation following ischemic stroke through the production of pro-inflammatory factors such as IL-1β, TNF-α, and IL-6,28 we assessed the expression of these pro-inflammatory factors in both MCAO and OGD/R models." (PMID 40831534, 2025). "Studies demonstrate that the Sirt1-Bmal1 pathway also plays a crucial role in ischemic stroke, exerting regulatory effects in the early stages by modulating the expression of oxidative stress and inflammatory markers such as MDA, SOD, IL-6, and Tumor Necrosis Factor-alpha." (PMID 40527853, 2025). "The results showed significantly higher levels of MDA, IL-6, TNF-α, and lower expression of SOD in the ischaemic stroke group compared to the control group, indicating the involvement of oxidative stress and inflammation in the early pathological progression of ischaemic stroke." (PMID 38245621, 2024). "Likewise, increased plasma levels of IL-1β, IL-6, and TNF-α have been reported in ischemic stroke patients." (PMID 36536168, 2024). "IL-6 and TNF-α are the major inflammatory factors released following ischemic stroke." (PMID 36755018, 2023).
ischemic stroke (continued). "The purpose of the research was to assess the concentration of pro-inflammatory cytokines IL-6 and TNF-α in the blood serum of patients with ischemic stroke (AIS) and to investigate their role as new markers in predicting functional prognosis after thrombolytic therapy." (PMID 36142524, 2022). "IL-6 stimulates the phosphorylation of STAT3 and the early transcriptional activation of angiogenesis-related genes, thereby leading to the enhanced angiogenesis and elevated cerebral blood flow in the delayed period after ischemic stroke." (PMID 35173738, 2022). "In addition, other top immune genes are IL6 and TNF, which are also important immunoinflammatory molecules that participated in ischemic stroke." (PMID 35419038, 2022). "In addition, ELISA showed that levels of pro‐inflammatory factors (IL‐1β, IL‐6, TNF‐α) were increased after ischemic stroke." (PMID 35695696, 2022). "For example, an article published by Brain Behavior and Immunity focuses on a natural product, pinocembrin, which has been shown to improve neuroinflammation and effectively reduce the expression of inflammatory factors such as IL-6,TNF-α in the brain tissue of patients with ischemic stroke." (PMID 36389810, 2022). "The same frequency interval (1–20 Hz) may reduce the levels of pro-inflammatory cytokines, including IL-1b, IL-6, and TNF-α, in rats following ischemic stroke." (PMID 35055089, 2022). "In addition, proinflammatory cytokines, including IL-1, IL-6, IL-17, and TNF-α, have been detected in the brain of ischemic stroke patients and the infarction area of animal models." (PMID 33777318, 2021). "Future work will explore whether blockade of the potential mediators of enhanced neutrophil pathogenicity (IL-6, CXCL1) identified in these experiments can ameliorate the worse ischemic stroke outcomes seen in aged animals." (PMID 31927534, 2020). "MALAT1 could bind to IL-6, E-selectin and MCP-1, which prevent OGD/R-induced inflammatory response in ischemic stroke by reducing the production of proinflammatory cytokines." (PMID 33613191, 2020). "The group deduced that IL-6 also has a neuroprotective role in the cascade of inflammation during an ischemic stroke, not just a damaging one." (PMID 32899616, 2020). "Higher levels of CRP (C-reactive protein), but not interleukin-6 (IL-6) or the CRP level relative to that of IL-6, were associated with increased risk of ischemic stroke in population-based studies." (PMID 30999680, 2019). "In addition, EA treatment inhibits microglia-mediated neuroinflammation through inactivation of p38 MAPK and MyD88, accompanied by the decrease of IL-1β, IL-6, and TNF-α after ischemic stroke." (PMID 31866829, 2019). "Ischaemic stroke induced massive production of TNF‐α, IL‐1β and IL‐6 in Iba‐1+ cells." (PMID 31087489, 2019). "The MCAO challenge itself induced a significant up-regulation of pro- and anti-inflammatory genes in the brains of both control and treatment animals, including IL-6, IL-1β, TNF-α, IL-10, CCL2, and CCL3, indicating a pivotal role of neuroinflammation in the pathology of acute ischemic stroke events." (PMID 30126083, 2018). "1–20 Hz EA treatment were inserted at 2–3 mm depth into Quchi and Zusanli, and may reduce the levels of pro-inflammatory cytokines, including IL-1β, IL-6, and TNF-α, in rats following ischemic stroke." (PMID 30618558, 2018). "In order to elucidate factors that affect the clinical course of ischemic stroke, IL-6 and IL-17A levels were analyzed in patients not complicated with infection (non-SAI)." (PMID 23936327, 2013). "Moreover, ischemic stroke patients have higher levels of oxidative stress and inflammatory markers, such as IL-6, TNF-α, MDA, and SOD, than non-stroke patients." (PMID 41567643, 2025). "Enhanced knowledge of the roles played by IL-6 and TNF-alpha may lead to novel therapeutic strategies that can optimize recovery and improve the overall quality of life for individuals affected by ischemic stroke." (PMID 39859987, 2025).
ischemic stroke (continued). "Therefore, the most significant 4 genes were PIK3CA, IL6, TNF, and KNG1, which means these molecules may function as important immune regulators in the inflammatory response following ischemic stroke." (PMID 35419038, 2022). "Interleukin-6 has also been studied in ischemic stroke, but its role has not been clarified." (PMID 28936196, 2017). "Furthermore, the increased incidence of ischemic strokes and intracerebral hemorrhage (ICH) could be explained by the increased vascular permeability and increased complement and coagulation cascades mediated by increased interleukin-6 (IL-6) and D-dimer." (PMID 37876390, 2023). "In addition, it was shown that IL-6 might promote early clinical deterioration of ischemic stroke, and TNF-α did not play a role in early clinical deterioration." (PMID 35111052, 2021). "When an ischemic stroke occurs, the lack of α9 in neutrophils limits the inflammatory response by lowering TNF-α, IL-1β, and IL-6 levels." (PMID 39649720, 2024). "Additionally, GSVA showed oligodendrocyte subcluster 9 was enriched in IL-6, complement, TNF-α pathway, and Kras signaling, suggesting that Sgk3 from oligodendrocytes may play an important role regulating oligodendrocyte viability and inflammatory responses during the acute stage of ischemic stroke." (PMID 33692998, 2021). "We showed that salivary TNF-α and IL-6 were significantly higher, whereas IL-10 content was statistically lower in both non-stimulated (NWS) and stimulated (SWS) whole saliva of ischemic stroke patients." (PMID 34433866, 2021). "The roles of IL-6 and TGF-β in ischaemic stroke and BBB disruption are however not fully elucidated." (PMID 31666540, 2019). "In the clinical part of this study, the quantitative analysis demonstrated circulating TMEM166, interleukin 6 (IL-6), and C-reactive protein (CRP) levels were significantly elevated in patients who suffered an ischemic stroke after CEA compared to those who did not." (PMID 37611898, 2024). "Secondly, ischemic stroke, including MCAO, can trigger a cascading pathological noninfectious neuroinflammation and the subsequent excessive release of proinflammatory cytokines, including interleukin-1 (IL-1), tumor necrosis factor alpha (TNF-α), and interleukin-6 (IL-6)." (PMID 33551726, 2020).